BDNF (brain derived neurotrophic factor)
Diseases named in the same sentence as BDNF in open-access papers (continued):
Sharing a sentence is not in itself a finding about the gene and the disease.
Cognitive impairment (continued). "Establishing reference BDNF levels in seronegative controls would aid in validating BDNF as a biomarker for HIV-associated cognitive impairment." (PMID 39548055, 2025). "Human genetic and experimental animal studies suggest that declined BDNF levels are associated with synaptic and neuronal loss and cognitive impairment with aging and AD." (PMID 40380033, 2025). "It has been shown that hippocampal BDNF levels decrease in an experimental PD model in rodents and that this decrease is associated with cognitive impairment." (PMID 40208367, 2025). "Elevated phenylalanine levels have been confirmed to cause cognitive impairment and brain abnormalities, potentially by reducing BDNF mRNA and protein expression, thereby diminishing neurite development and promoting neuronal death." (PMID 41155481, 2025). "Cognitive impairments in bipolar disorder patients can be classified into distinct subgroups, which are associated with serum levels of BDNF and CRP." (PMID 41367212, 2025). "Reduced serum BDNF levels were associated with mild cognitive impairments, AD, and depression-related disorders." (PMID 39696694, 2024). "A meta-analysis suggests that BDNF Val66Met is associated with cognitive impairment in Parkinson’s disease, confirming that BDNF is a risk factor for this disorder." (PMID 38648255, 2024). "Loss of neurotrophic factors especially BDNF can lead to synaptic dysfunction, impaired autophagy, disturbed protein folding, and finally cognitive impairment." (PMID 37712973, 2024). "Obesity is associated with cognitive impairment and reduced levels of circulating brain-derived neurotrophic factor (BDNF), a protein crucial for brain function and health." (PMID 38785805, 2024). "It is suggested that probiotics supplementation potentially upregulates BDNF expression and its related signaling pathways through the gut-brain axis, thereby supporting neural plasticity and mitigating cognitive impairments associated with heat stroke." (PMID 38654189, 2024). "Although the mechanisms of BDNF loss-induced neurogenesis dysfunction are still unclear, it has been reported that low levels of BDNF in the serum were associated with cognitive impairment in patients with cancer and animal models." (PMID 38348396, 2024). "Other results suggest neurotrophin signaling deficits of BDNF are associated with alcohol-induced cognitive impairment." (PMID 38928583, 2024). "There is also an association between peripheral BDNF levels and cognitive deficits in patients with SZ60–63." (PMID 39039065, 2024). "Recent studies in which rats received a prolonged APAP treatment found strong associations between the expression of BDNF and the level of cognitive impairment." (PMID 38250995, 2024). "BDNF, a crucial factor in various brain processes, has been studied as a marker of neuropsychiatric diseases and has been linked to cognitive impairment in neurological disorders." (PMID 38592583, 2024). "In diabetes, adipose tissue-brain EV trafficking facilitates the transfer of miR-9-3p into the brain, causing synaptic damage and cognitive impairment by targeting brain-derived neurotrophic factor (BDNF)." (PMID 38160178, 2024). "BDNF is a neurotransmitter modulator that plays a key role in neuroplasticity and protects against neuroinflammation and neuronal apoptosis; decreased levels of BDNF are associated with AD and mild cognitive impairment." (PMID 39421246, 2024). "In contrast, marked cognitive deficits have been described in reports on patients with BDNF heterozygosity or mutations in the gene encoding for TrkB and NTRK2." (PMID 37491857, 2024). "Changes in neurotrophic factors levels, e.g., brain-derived neurotrophic factor (BDNF) is also linked to cognitive deficit." (PMID 37712973, 2024). "In contrast to AD animal models, activation of 5-HT1AR enhances hippocampal BDNF expression in mouse models of depression, cerebral ischemia, and cognitive impairments associated with schizophrenia." (PMID 39500357, 2024).
Cognitive impairment (continued). "In MIBC patients, a reduction in peripheral BDNF serum concentration suggests a potential association with increased stress and cognitive impairment, as has been shown in patients with progressed cancer and more anxious coping responses to the disease." (PMID 39684475, 2024). "Alterations in neurofilament, PSD-95, and brain-derived neurotrophic factor (BDNF) were key molecular changes identified in our study that were associated with cognitive impairment 1 month after recovery from systemic inflammation." (PMID 39266325, 2024). "Impaired BDNF signaling in AD is associated with Tau hyperphosphorylation, Aβ deposition, neuroinflammation, neuronal apoptosis, and cognitive impairment." (PMID 39500357, 2024). "Previous studies have shown that lower BDNF concentrations are associated with cognitive impairment, obesity, and metabolic syndrome, while higher BDNF concentrations are associated with improved cognitive performance and metabolic health." (PMID 38276070, 2024). "In traumatic brain injury, which caused mitochondrial impairments, anxiety and cognitive deficits, transplantation of allogeneic liver-isolated mitochondria restored astrocytic brain-derived neurotrophic factor (BDNF) levels and the behavioral deficits." (PMID 38474374, 2024). "Administration of ASA, CM, or a combination of both mitigated these hippocampal damages and cognitive deficits, elevated BDNF and CDNF levels, and alleviated the CA1 necrosis caused by EB." (PMID 39262160, 2024). "Low levels of BDNF can affect cognitive health and have been associated with cognitive impairment, difficulties in learning and memory processes and greater chances of making unhealthy decisions." (PMID 38442097, 2024). "This study indicates that multiple single nucleotide polymorphisms (SNPs) within the BDNF gene, including rs6265, rs11030104, rs7103411, and rs988748, are associated with serum BDNF levels in patients with Mild Cognitive Impairment (MCI)." (PMID 39876995, 2024). "A clinical trial (Phase 1) of gene therapy utilizing AAV2-BDNF (encoding brain-derived neurotrophic factor) to address early Alzheimer’s disease (AD) and mild cognitive impairment in 12 participants is currently ongoing." (PMID 38203812, 2024). "Multiple lines of evidence suggest that amyloid-beta (Aβ) can induce cognitive impairment and memory loss by downregulating BDNF expression." (PMID 39226164, 2024). "There is also evidence that serum brain-derived neurotrophic factor (BDNF), including its levels and gene polymorphism, contribute to the mechanism of cognitive deficits in BD-II depression." (PMID 38714952, 2024). "Because of the diverse roles of the BDNF-TrkB pathway, the dysregulation of BDNF-TrkB signaling has been implicated in various disease conditions, including cognitive impairment, obesity, neurodegenerative diseases, and cancer." (PMID 38254691, 2024). "administered antibiotics to adult mice and demonstrated that the resultant cognitive deficits were associated with brain region-specific changes in BDNF, NMDA receptor subunit 2B, serotonin transporter, and NPY." (PMID 37404311, 2023). "Evidence on a common polymorphism in the BDNF gene, known as Val66Met, has associated it with various psychiatric disorders, cognitive impairment, and changes in brain structure and function." (PMID 37109038, 2023). "As indicated by EPM, NOR, OLM, and Morris Water Maze tests, EE exposure ameliorates postsurgery SD‐induced cognitive impairments and neuron loss with upregulated BDNF and p‐GluA1(Ser845) expression." (PMID 37095708, 2023). "In this study, we examined the causal role of the BDNF-TrkB pathway in the ELS-induced cognitive deficits and evaluated the therapeutic effects of 7,8-DHF, the TrkB agonist attracting widespread attention for its cognition-enhancing effects." (PMID 37225683, 2023). "We find that FEP showed a walking delay and lower BDNF levels compared to HCs, which were associated with cognitive impairment and severity of symptoms." (PMID 37234686, 2023).
Cognitive impairment (continued). "Microglial-derived BDNF influences synaptic plasticity and a reduced expression of BDNF associates with altered behaviours and cognitive deficits." (PMID 37332846, 2023). "The presence of BDNF gene rs6265 polymorphism showed an increased probability (3.6 times) of global cognitive impairment." (PMID 38136952, 2023). "Other studies have shown a gradual increase of BDNF levels associated with severity of cognitive impairment." (PMID 36979505, 2023). "While low levels of BDNF are associated with cognitive deficits and impaired memory and learning, increasing BDNF levels in AD animals prevents neuronal loss and improves cognitive performance." (PMID 36937673, 2023). "Accordingly, BDNF deficiency has been associated with memory and cognitive impairments in neurodegenerative diseases, including Alzheimer’s disease, and also with memory deficits in TLE." (PMID 37456525, 2023). "We aimed to evaluate the association between BDNF gene rs6265 polymorphism and cognitive impairment in Mexican patients with MS by performing a case–control study." (PMID 38136952, 2023). "Lower serum BDNF levels have been linked to the severity of cognitive impairment, and numerous investigations have revealed that individuals with T2DM have considerably lower BDNF levels than healthy subjects." (PMID 37113152, 2023). "Based on our findings and others from the literature, signaling cascade deregulations linked to pro-BDNF/m-BDNF balance are clearly involved in the cognitive impairment observed in stress-related disorders." (PMID 36901924, 2023). "To assess the risk factors for cognitive impairment in the acute period of ischemic stroke, we performed a binary logistic regression analysis using the type of ischemic stroke, BDNF concentration, and NIHSS 1st day score as predictors." (PMID 36969561, 2023). "Not only aging but also low levels of education were seen to be associated with decreased levels of BDNF, which further correlate with the severity of cognitive impairment, since AD patients were shown to express the lowest levels of BDNF." (PMID 37686802, 2023). "From the genetic perspective, the presence of BDNF genetic polymorphism at codon 66, the Met66 allele, was also significantly associated with cognitive impairment as MCI progressed to AD and interacted with ApoE 4111,112." (PMID 38053647, 2023). "Our past human studies have shown that the reduction of BDNF levels is linked with acute and persistent self-reported cognitive impairments in cancer survivors treated with cytotoxic agents including cyclophosphamide and ADR." (PMID 36720792, 2023). "It was demonstrated that an increase in BDNF level leads to a decrease in the risk of cognitive impairment (OR = 0.98, 95% CI 0.98–0.99, p=0.010) and an atherothrombotic subtype of ischemic stroke increases it (OR = 10.48, 95% CI 1.53–71.69, p=0.017)." (PMID 36969561, 2023). "We found that a low level of BDNF and a thrombotic subtype of ischemic stroke can be risk factors for cognitive impairment in the acute period, which can be useful in planning treatment and rehabilitation measures." (PMID 36969561, 2023). "In this study, we examined the causal role of the BDNF-TrkB pathway in DG in ELS-induced cognitive deficits in adult male mice." (PMID 37225683, 2023). "It has been demonstrated that cognitive impairment occurs in neurodegenerative disorders and is linked to a reduced blood BDNF." (PMID 36834322, 2023). "In summary, cognitive function was lower in the FEP than in HC while the FEP had a walking delay and lower BDNF levels than that of the HC, which were associated with cognitive impairment and symptom severity." (PMID 37234686, 2023). "The proposed test allows predicting the risk of cognitive impairment in the acute period of ischemic stroke depending on the hemodynamic subtype and BDNF concentration for 1 day (AUC = 0.85 ± 0.06 (95% CI 0.74–0.97), p < 0.001)." (PMID 36969561, 2023).
Cognitive impairment (continued). "An association between higher baseline BDNF levels and a lower rate of cognitive impairment progression over 1 year in Alzheimer's disease has also been reported." (PMID 36969561, 2023). "Several studies have linked reductions in BDNF to the pathogenesis of cognitive disorders, such as AD, with low serum levels correlated with AD and mild cognitive impairment and high serum levels associated with better cognition in healthy older adults." (PMID 36720792, 2023). "In schizophrenia, abnormal levels of neurotransmitters that interact with BDNF have been linked to cognitive impairments and psychotic symptoms." (PMID 37809845, 2023). "In this sense, both primary and secondary sleep disorders have been associated with reduced serum BDNF levels and with the subsequent development of cognitive impairment, as seen during aging." (PMID 37108547, 2023). "For this reason, interventions resulting in a transient BDNF level increase, e.g., physical exercise, diet, social activity, and education (which can reduce long-term risk of cognitive impairment and dementia), probably will be insufficient for ASD patients." (PMID 37239153, 2023). "Taken together, our results suggest that BDNF and its TrkB receptor are causally involved in the cognitive impairment caused by early-life stress, which can serve as the treatment targets for the cognitive deficits of stress-related psychiatric disorders." (PMID 37225683, 2023). "One of the variables that has been associated with cognitive impairment in BD is the Brain-Derived Neurotrophic Factor (BDNF)." (PMID 38250270, 2023). "This study investigated the association of plasma BDNF levels with cognitive impairment and its influencing factors." (PMID 36425322, 2022). "BDNF shares an important link with brain aging by preventing age-driven cognitive impairments and synaptic loss." (PMID 35966795, 2022). "Neurotrophic factors and their corresponding receptors, particularly BDNF/TrkB and NT-3/TrkC, are associated with cognitive impairment and AHN." (PMID 35309893, 2022). "A possible mechanism by which sevoflurane causes cognitive impairment is through impaired transcription of mRNA encoding brain-derived neurotrophic factor (Bdnf)." (PMID 35813070, 2022). "Since there were significant difference between CNC, MCI, and DAT cohorts regarding age, sex, education, and social status, the factors influencing the association between plasma BDNF and cognitive impairment were analyzed separately." (PMID 36425322, 2022). "Our lab has previously shown that elevated H3K9me3 in aged mice is correlated with synaptic loss, cognitive impairment and a reduction in brain derived neurotrophic factor (BDNF)." (PMID 35821854, 2022). "The systematic review suggests a possible association between stressors, functional and cognitive impairment, and BDNF and/or inflammatory factors but the small number of studies do not permit to establish solid conclusions." (PMID 35740389, 2022). "It is very important to study and control the influence of these factors on the association between BDNF levels and cognitive impairment, and it is more important to consider the possible influence of various factors in the interpretation of results." (PMID 36425322, 2022). "BDNF deficient populations, such as those who have cognitive impairment, benefit from a hypocaloric diet to help BDNF regulation." (PMID 36138878, 2022). "Blood BDNF concentration decreases with aging, type 2 diabetes (T2D), and obesity, which are all associated with cognitive impairment." (PMID 35998179, 2022). "The Met allele decreases neuronal dendrite distribution and targeting to secretory granules, lowering extracellular BDNF levels and causing cognitive impairment." (PMID 35743271, 2022). "In the present study, the association of plasma BDNF with AD cognitive impairment and influencing factors was investigated in depth based on a large sample of elderly people in the community." (PMID 36425322, 2022).
Cognitive impairment (continued). "Cognitive impairment with advancing age is associated with reduced expression of BDNF and results of various studies have reported reduced concentrations in aged rodents, primates, and humans." (PMID 35692417, 2022). "Recent studies have shown that VD can elevate ACH levels and attenuate the resulting cognitive impairment by inhibiting the expression of neuroinflammatory factors including IL-1β, BDNF, and NF-κB caused by a high-fat diet." (PMID 35754958, 2022). "In conclusion, GTDE increases antioxidant capacity and BDNF expression of the brain, protects the dendritic structure of neurons, and reduces aging-induced neuronal damage, thereby attenuating cognitive impairment caused by aging." (PMID 35390035, 2022). "Its hyperactivation leads to the reduction of BDNF in the hippocampus and frontal cortex, which can cause neurological and cognitive impairment; Its inhibition can also affect synaptic plasticity and cognitive function and downregulate BDNF." (PMID 36504660, 2022). "Taken together, these findings support the conclusion that inhibition of AHN at least partially lead to cognitive impairment caused by sevoflurane, which is probably attributed to the downregulation of BDNF/TrkB and NT-3/TrkC pathways." (PMID 35309893, 2022). "Higher serum levels of CA-125, FABP, and TNF-alpha as well as lower serum levels of BDNF were associated with cognitive impairment as measured by MoCA scores and with motor impairment assessed by H&Y staging in males and/or females." (PMID 35280273, 2022). "Reduced BDNF levels in the human brain are associated with cognitive impairment caused by neurodegenerative diseases, such as Alzheimer's disease and Parkinson's schizophrenia." (PMID 36683819, 2022). "It is well documented that cognitive impairments in some neurological diseases are associated with reduction of BDNF levels." (PMID 35656440, 2022). "The carriers of at least one BDNF 66Met allele presented a higher prevalence of cognitive impairment." (PMID 35743271, 2022). "BDNF was associated with higher degree of cognitive impairments, the other proteins showed a protective effect on cognitive functioning." (PMID 35148403, 2022). "In clinical studies, it was found that REST and BDNF gene polymorphisms can be used as markers for the diagnosis of cognitive impairment in epilepsy." (PMID 36065764, 2022). "Lower circulating BDNF levels are associated with cognitive impairment and age-related hippocampal atrophy." (PMID 35998179, 2022). "BDNF single-nucleotide polymorphism modulates the association between beta-amyloid (Aβ) and hippocampal disconnection in AD and is an important factor in cognitive impairment in AD." (PMID 35769604, 2022). "Cognitive impairment is associated with methylation modifications of a variety of genes, commonly including BDNF, the Reelin genes, the serine/threonine protein phosphatase 1 gene, and many others." (PMID 36504660, 2022). "Chronic administration of curcumin, the main active ingredient in turmeric, alleviates AD-associated cognitive impairments via upregulating BDNF/ERK and Akt/GSK3β signaling in the hippocampus." (PMID 35090576, 2022). "BDNF Val66Met polymorphism has also been shown to protect against cognitive impairment and improve motor recovery in MS patients." (PMID 35743271, 2022). "Our work unmasks the ameliorating effect of EA twig extract 2 on scopolamine-associated cognitive impairments through the restoration of cholinergic systems and the BDNF/ERK/CREB pathway." (PMID 36615789, 2022). "Cognitive deficits are associated with altered levels of several neurological factors, such as brain-derived neurotrophic factor (BDNF), nerve growth factor (NGF), and glial cell-derived neurotrophic factor (GDNF)." (PMID 36329874, 2022). "The present review explored putative biomarkers implicated in MS-related alterations such as the role of BDNF and the Tryptophan/Kynurein ratio on cognitive deficits and eventual neuroprotection." (PMID 35745113, 2022).